CD80 (CD80 molecule)
Diseases named in the same sentence as CD80 in open-access papers (continued):
Sharing a sentence is not in itself a finding about the gene and the disease.
tumor (continued). "M1 macrophages are tumor-resistant and can be identified by different phenotypic markers, including CD80/B7-1, CD86/B7-2, HLA-DR, and NOS2." (PMID 39599846, 2024). "The percentage of mature DCs, characterized by dual‐positive CD86 and CD80 signals, increased from 23.4 to 75.3% in the CD11c+ cell subset of the tumor." (PMID 38774917, 2024). "Tumor cells were labeled with the anti-CD80 antibody in 28 cases (72%), mostly myelomonocytic and monocytic/monoblastic variants." (PMID 39224452, 2024). "Dendritic cells, which mainly serve to activate tumor-specific cytotoxic T cells, also interact with MM plasma cells by CD80/86–CD28 binding." (PMID 38654298, 2024). "Tumor cell suspensions prepared from tumor tissue were labeled and analyzed using the following panel macrophage (F4/80+ CD11b+), M1 macrophage (F4/80+ CD80+) and M2 macrophage (F4/80+ CD260+)." (PMID 38974834, 2024). "When the PD-1/PD-L1 and CD80/PD-L1 pathways are activated, the ability of T cells to kill tumor cells is impaired." (PMID 39635528, 2024). "The DC/tumor fusion cells that we produced had strong expression of maturity-associated markers (MHC II, CD80, and CD86) as well as both types of fluorescence." (PMID 38824143, 2024). "The bindings of PD-1 and CTLA-4, expressed on activated T cells, to their ligands on tumor cells (PD-L1) or antigen-presenting cells (APCs) (CD80/CD86) restrain the anti-tumor T cell activities." (PMID 38280003, 2024). "The observed correlation of CD80 with tumor regression warrants further research into possible anti-tumor strategies in malignant histiocytic neoplasia." (PMID 38962703, 2024). "Clinically, we observed that patients with PD-L1+ tumour cells and high levels of circulating PD-1/CD80+ sEVs but low levels of PD-L1+ sEVs responded well to immunotherapy." (PMID 38719909, 2024). "The results showed that the disease was stable and the vaccine was safe, further demonstrating the feasibility of CD80 application in tumor vaccines." (PMID 39575257, 2024). "PD-1/L-1, CTLA-4, and CD80/CD86 interactions are two crucial immune checkpoint pathways in the tumor microenvironment (TME)." (PMID 38791528, 2024). "In contrast, the number of CD80 expressing tumor cells was found to increase with time in the central and top thirds of the tumor in this study whereas a recent study showed a decrease in its expression at the protein level." (PMID 39619201, 2024). "Initially, we probed the expression levels of CD86 and CD80 essential molecules for CTLA-4 interaction on tumor cells." (PMID 38473398, 2024). "CD80 promotes T cell activation and anti-tumor immune response by binding to CD28 on the surface of T cells." (PMID 39290697, 2024). "It was observed that in the tumour, gMFI of 2NBDG in CD80+ DCs and macrophages were significantly higher in PFK15 + F16BP(polyIC) MPs as compared to PFK15 only condition, however, these were not significantly different than no-treatment control." (PMID 37660049, 2023). "For this purpose, we generated T2 tumor cells with a double KO of both CD28 ligands CD80 and CD86 (termed “T2 KO”)." (PMID 36732507, 2023). "Proinflammatory CD80, CXCL10, anti‐inflammatory IL‐10, and the tumor‐associated markers MMP2, MMP7, MMP12, and MGLL showed lower baseline expression and were upregulated in macrophages as well." (PMID 38037545, 2023). "Our data supports a mechanism where CD80 is overexpressed by tumours cells after PDT, and sometimes also PD-L1 and CTLA-4." (PMID 37468749, 2023). "For instance, a tumor cell line can be engineered to express the co‐stimulatory marker CD80 to target CD28 on T cell surface." (PMID 37254712, 2023). "In some cancer cells, redaporfin-PDT also increases CTLA-4 and PD-L1 expressions and virtuous combinations between PDT and immune-checkpoint blockers (ICB) depend on CD80/PD-L1 or CD80/CTLA-4 tumour overexpression ratios post-PDT." (PMID 37468749, 2023).
tumor (continued). "The binding of CD80/CD86 on antigen-presenting cells to CTLA-4 on T-cells in the tumor microenvironment suppresses the immune system, enabling tumor proliferation." (PMID 37511453, 2023). "Tumor-derived EVs containing miR-424 inhibit the expression levels of costimulatory molecule CD80 expressed on DCs and the expression of CD28 on Th cells and Tc cells, impairing T cell activation and proliferation." (PMID 37175226, 2023). "The remarkably increase in the survival of mice with CT26 tumours treated with the combination of αCTLA-4 with redaporfin-PDT can be assigned to the high surface expression of CD80 and unchanged expression of CTLA-4 post-PDT." (PMID 37468749, 2023). "The expression of NUPR1 was highly correlated with tumor‐associated macrophage markers including CCL2, CCR5, CD80, and CD86." (PMID 36468653, 2023). "These genes included those related to P/DAMP signaling (e.g., Il6, Tlr1, Tlr4, Il1b, Il18), necroptotic tumor cell death (e.g., Casp1, Casp8, Il1b), and activation of the adaptive immune system (e.g., Cd80, Cd8a, Ccr5, Cxcl10)." (PMID 37213298, 2023). "After the tumor antigen is presented, the B7 (CD80/CD86) receptor on the surface of APCs is bound by the CTL-associated CD28 receptor, thereby activating CTL." (PMID 37089933, 2023). "Our results indicate that B-LNP treatments induced TAMC expression of co-stimulatory factors (CD40, CD80, CD86) and enhanced tumor-associated antigen presentation, and, importantly, impaired TAMC immunosuppressive activities." (PMID 36959214, 2023). "Mice immunized with leukemic tumor cells that overexpress CD80, a costimulatory molecule that plays a role in T-cell activation, exhibit resistance to tumor growth." (PMID 37894750, 2023). "Exposure of DCs to the 33% Cu-doped TiO2 NPs resulted in higher levels of MHCII, as was also observed for DCs in the tumor-draining lymph nodes, insignificantly affected activation markers CD80 or CD86." (PMID 36915084, 2023). "On this basis, we further investigated the relation between CD80 expression and clinical traits, such as age, gender, stage, tumor (T), node (N), and metastasis (M)." (PMID 36892747, 2023). "Antibodies against CTLA-4, PD-1 and PD-L1 can block the binding of CTLA-4 & CD80/86 on antigen presenting cells (APC) or the binding of PD-1 and PD-L1 on tumor cells, which can lead to binding of TCR and MHC causing T cell activation." (PMID 37064866, 2023). "Expression levels of B7-H3, PD-L1, Tim-3, LAG3, VISTA, and STING as well as of CD40 and CD80 were significantly elevated in tumor boundary CD11c+ segments." (PMID 38044986, 2023). "Durvalumab blocks the binding of PD-L1 to its receptors PD-1 and CD80 in order to aid in the anti-tumor T cell response activation." (PMID 36816749, 2023). "For instance, CD80 is activated by CTLA-4, and the transfection of human tumor cells with CD80 prevents PD-L1-mediated immunosuppression by tumor cells and restores T cell function." (PMID 37686682, 2023). "The results show different densities of macrophage infiltration (M1/CD80 or M2/CD163) in both the tumor stroma (ST) and intratumoral (IT) areas." (PMID 37628994, 2023). "Interaction between CTLA-4 on T cells and CD80 on tumor cells leads to protein kinase B (Akt) pathway inhibition and IL-2 function in T cells." (PMID 36816749, 2023). "We noted direct coculturing increased stemness among CSC populations and induced both M1 (CD80 and HLA-DR) and M2 (CD163) tumor associated macrophage polarization." (PMID 37249733, 2023). "Tumor vaccines transfected with the CD80 gene restored tumor‐specific T cell activation and reversed PDL1‐mediated immunosuppression." (PMID 37476068, 2023). "While PD-L1 was similarly upregulated, the AT3 tumours were still able to engage immune evasive strategies by downregulating CD80 and CD86 molecules." (PMID 37582853, 2023). "The interaction of CD80 with CTLA-4 on T cell subsets can enhance the immune response against tumor cells by inactivating the tumor microenvironment." (PMID 37305822, 2023).
tumor (continued). "The concurrent expression of CD80 and PD-L1 on the surface of the same tumour cells will promote cis-CD80:PD-L1 interactions." (PMID 37468749, 2023). "Proinflammatory CD80, anti‐inflammatory CD206, CCL18, and CCL22, and the tumor‐associated markers including MMPs, MGLL, and TLR4 were expressed by a low proportion of monocytes (<1%), but significantly upregulated in TAM." (PMID 38037545, 2023). "Mice receiving adjuvant NIPP treatment after surgical resection of orthotopic breast cancer tumors showed an increased percentage of mature CD86+ and CD80+ DCs in tumor-draining lymph nodes, and increased numbers of tumor-infiltrating CD4+ and CD8+ T cells." (PMID 36831415, 2023). "In the context of the tumor microenvironment, reduction of CD80-expression in cancer cells is a powerful mechanism of immune response evasion." (PMID 36900266, 2023). "Our studies of MDMs suggest that some of these are M1-polarized MΦ, but based on CD68, CD80, CD163, and CD206, which are typically used for MΦ polarization, it is apparent that tumor-associated MΦ subsets occupy a broad spectrum within this classification." (PMID 38322012, 2023). "The maturation level of DCs (CD11c+/CD80+/CD86+) in the tumor-draining lymph nodes was first analyzed by flow cytometry." (PMID 37296221, 2023). "Tumour-infiltrating DCs process and present tumour antigens and gradually differentiate into mature DCs that express co-stimulatory molecules CD80 or CD86 to interact with T cells to resist tumours." (PMID 36463323, 2023). "In tumors, PD-1 or CTLA-4 is expressed on CD8+ T cells and binds to PD-L1 or CD80/CD86 expressed on tumor cells and tumor-infiltrating myeloid cells (e.g., TAMs), respectively." (PMID 37345660, 2023). "Preclinically, the treatment of mice bearing OC with either anti-CTLA4 or its ligand CD80 was shown to slow down the tumor growth and reduce T-cell suppression by MDSC through direct cell–cell interaction." (PMID 37513979, 2023). "CD80 plays an important role in T-cell activation, exerting a dual effect on tumor immunity: it binds to CD28 to provide a costimulatory signal for T-cell activation, and it binds to CTLA-4, resulting in an immunosuppressive effect." (PMID 37765273, 2023). "M1 macrophages express cell surface markers such as CD80, CD11c and are considered to exert largely anti-tumour effects." (PMID 37108548, 2023). "When CD80 expression in tumor tissues was examined by immunohistochemistry (IHC) staining, it was observed that the expression of CD80 increased after the SuperPDL1exo treatment." (PMID 37529049, 2023). "As the results suggested, the expression of CD80 was lower in LUAD tumor tissues than in normal tissues (p < 0.05)." (PMID 36892747, 2023). "A significant (p < 0.01) upregulation of the CD11c+CD80+CD86+ cell (matured DC) proportion in tumour draining lymph nodes was detected after US+CA treatment compared to untreated tumours (26.40 ± 3.70% vs. 13.03 ± 2.03%)." (PMID 37631324, 2023). "Supernatants from irradiated tumor cells induced elevated expression of CD80 and CD86 on the surface of DCs and a 4-fold increase in infiltration of CD11b+CD11c+MHC-II+ DCs." (PMID 37833255, 2023). "The maturity of DC/tumor fusion cells is usually determined by costimulatory molecules (e.g. CD80, CD86, as well as NHC-II) expression levels." (PMID 37419930, 2023). "For instance, CD80 signal transduction can delay tumor proliferation and induce apoptosis by up-regulating the expression of pre-apoptotic molecules and down-regulating anti-apoptotic molecules." (PMID 37510310, 2023). "Specifically, we find that rhythmic trafficking of DCs to the tumour draining lymph node governs a circadian response of tumour-antigen-specific CD8+ T cells that is dependent on the circadian expression of the co-stimulatory molecule CD80." (PMID 36470303, 2023).
tumor (continued). "Immune checkpoint blockade (ICB) is the strategy to block the binding of immune checkpoints to their cognate antigens, PD-L1 and B7/CD80, respectively, with the aim to reactivate T cells inside the tumor." (PMID 36831412, 2023). "PD-L1 expressed on the surface of tumour cells acts as a molecular shield to prevent cytolysis mediated by T cells because PD-1:PD-L1 interaction antagonizes CD28:CD80 co-stimulation." (PMID 37468749, 2023). "Among these cancer types, tumor-associated macrophage (TAM) markers such as CCL2, CD68, CD80, and IL10 had strong or moderate correlations with NNMT expression." (PMID 36817086, 2023). "By real-time RT-PCR analysis, we observed that the expression of Cd80 and Cd86 tended to be lower in the tumor of S100a4-Cre; Ext1f/f mice and a significant difference in Cd80 expression was observed." (PMID 36809261, 2023). "PD-L1 shows widespread expression in tumor cells, whereas CD80 is expressed primarily on antigen-presenting cells, including dendritic cells, and is upregulated after these cells are activated." (PMID 36470427, 2022). "Further, miR-125b inhibits M2 polarization through the repression of IRF4 and, when overexpressed in macrophages, increases in vitro CD8+ T-cell priming, tumor clearance, and CD80/86, CD40, MHCII, and IFN-γ receptor (IFN-γR) expression." (PMID 36248881, 2022). "In the lymph node, naive CD8+ T cells that receive tumor antigens must be activated by the co-stimulatory signal through binding CD80/86 of DC cells to CD28 of T cells to become cytotoxic CD8+ T cells." (PMID 35159059, 2022). "PD-1 and CD80 blockade reduces tumor egress of PD-1high fragile Tregs and Teffs into draining lymph nodes, respectively, and promotes tumor regression." (PMID 35449134, 2022). "We also demonstrate that increased neutrophil infiltration correlates to inhibited tumor immune status, and that the activated CD80/CD86-CTLA4 axis in inflammation participates in the T cell exhaustion." (PMID 36443332, 2022). "We also observed an upregulation of CD80 on DCs in 4T1 tumor-inoculated mice, indicating that DCs in mLNs were activated." (PMID 36232335, 2022). "PD-L1 binds to PD-1 or CD80 (B7-1) on activated T cells to mediate an inhibitory signal and to prevent the immune system from rejecting the tumor." (PMID 35917184, 2022). "The aim of this study is to investigate the interlinkage between MALAT1 and HOTAIR and their regulatory activity on immunomodulation by examining the expression profile of CD80 and MSLN in tumor-associated macrophages in the hormonal, HER2+, and TNBC subtypes." (PMID 36387279, 2022). "Given the complexity of the GBM immune microenvironment, disrupting CTLA-4/CD80 complex formation in the tumor was found to contribute to the improved survival of GBM-bearing mice." (PMID 36466873, 2022). "In the TME, receptors of PD-L1 and CD80 expressed by tumor cells or tumor-related immune cells can interact with PD-1 and CTLA-4 expressed by CD8 T cells, respectively, to impair CD8 T cell function." (PMID 35265130, 2022). "It has been reported that transforming growth factor-b induced CSCs of CD80 expression, an immune cell surface ligand, to block cytotoxic T-cell activity and mediate tumor resistance to adoptive cytotoxic T-cell transfer-based immunotherapy." (PMID 36685583, 2022). "Using this model, the anti-tumor activity of ALPN-202 was significantly improved relative to WT CD80 Fc or anti-human PD-L1 treatment." (PMID 35379805, 2022). "For example, CD80 expression can prevent PDL1-mediated immunosuppression of tumor cells and restore T cell activation." (PMID 36311731, 2022). "DC immune function in EC patients is impaired both at the circulation and tumor sites, accompanied by decreased CD80 and CD86 expression." (PMID 36106333, 2022). "The overexpression of PD-L1 and CD80/CD86 on tumor cells, which can respectively bind to PD-1 and cytotoxic T lymphocyte antigen 4 (CTLA4), results in the inhibition of T cell activation." (PMID 36013050, 2022).
tumor (continued). "Gene Expression Omnibus (GEO) dataset analysis showed that CD47 expression positively correlates with M1 marker CD80 and M1 abundance in tumor-infiltrating immune cells." (PMID 36274066, 2022). "We therefore investigated differential expression of PD-1, PD-L1, PD-L2, and CD80 ICs in young versus aged tumor-naïve and tumor-challenged mice." (PMID 36876140, 2022). "Tumor infiltrating dendritic cells, expressing both PD-L1 and CD80, appear to play a key role in regulating T-cell antitumor response." (PMID 36470427, 2022). "Programmed death-1 (PD-1) and cytotoxic T lymphocyte antigen-4 (CTLA-4) interact with their ligands found on the surface of antigen presenting cells (APC) or tumor cells (PD-L1/2 and CD80/86)." (PMID 35707528, 2022). "An in vivo study has shown that CD80-Fc protein is effective in slowing tumor growth and activating tumor-infiltrating T cells." (PMID 36480493, 2022). "Durvalumab blocks the binding of PD-L1 and PD-1 to CD80 to prevent tumour immune escape, activates and releases T cells, and induces an immune response." (PMID 36016159, 2022). "Studies have also demonstrated that CTLA-4 is constitutively expressed on tumor cell lines at various degrees of intensity and can trigger apoptosis of CTLA-4-expressing tumor cells after interaction with soluble CD80 or CD86 recombinant ligands." (PMID 36104728, 2022). "Compared to the control group (tumor cells co-injected with untreated macrophages), the treated group (tumor cells co-injected with macrophages pre-treated with SPIONs (+)) display an increase in CD80 (M1 marker) and a decrease in CD206 (M2 marker) in vivo." (PMID 36365207, 2022). "These Th-APCs with acquired pMHC I and costimulatory CD54 and CD80 molecules can stimulate tumor-specific CD8+ CTL responses and induce antitumor immunity." (PMID 36466863, 2022). "We also observed a reduction in the number of pro-tumorigenic M2 phenotypic (CD206+) macrophages and an increase in tumoricidal M1 phenotypic (CD80+) macrophages in the spleen, lymph node, and tumor with the combination treatment." (PMID 36551577, 2022). "A marked reduction of the CD80+ IFN-γ M1 macrophages was further noted in the same tumor tissues from IP6K1 KO mice." (PMID 35308129, 2022). "DC maturation was also studied by detecting the population of matured DCs (CD80+CD86+) in tumor-draining lymph nodes (TDLNs) by flow cytometry analysis." (PMID 35710545, 2022). "Studies have found that nab-paclitaxel internalization by tumor-associated macrophages can promote the activation of M1 macrophages and increase the MHC II+CD80+CD86+M1 macrophage." (PMID 35719979, 2022). "We found considerable, previously undescribed age effects on expression of various IC molecules participating in the ICI treatment, including PD-1, PD-L1, PD-L2, and CD80, in distinct organs and in the tumor." (PMID 36876140, 2022). "Young mice had a higher prevalence and number of tumor-infiltrating DC versus aged, but aged tumor-infiltrating DC had significantly higher CD80 and PD-L1 expression prevalence." (PMID 36876140, 2022). "It targets PD-L1 on tumor cells, inhibiting its binding to its receptors PD-1 or CD80 on the surface of T-cells." (PMID 35267561, 2022). "While in the C3PQ tumor model, central memory cytotoxic T cell infiltration was increased and the ratio of macrophages expressing CD80 was high." (PMID 35356198, 2022). "Total number of PD-L1/CD80 co-expressing DC was similar in tumors of aged versus young due to the higher number of tumor-infiltrating DC in tumors from young mice versus aged." (PMID 36876140, 2022). "PD-L1 is a membrane protein that is expressed on immune and tumour cells and inactivates T cells by inducing programmed cell death via heterodimer formation with CD80." (PMID 35626020, 2022).